MR1 (major histocompatibility complex, class I-related)
Diseases named in the same sentence as MR1 in open-access papers (continued):
Sharing a sentence is not in itself a finding about the gene and the disease.
infection (continued). "We postulate that additional MR1-restricted T-cell subsets may play a unique role in defence against infection by broadening the recognition of microbial metabolites." (PMID 27527800, 2016). "Furthermore, we have investigated the role of intracellular trafficking in MR1 presentation of ligands to MAIT cells in the context of intracellular infection with Mtb." (PMID 27031111, 2016). "In the case of the highly phagocytic THP-1 cell line, we set up a mutation enrichment strategy relying on the positive selection of THP-1 mutants unable to present MR1 Ags following infection with M. smegmatis and on MAIT cell cytotoxicity as a selecting force." (PMID 27307560, 2016). "Similarly, Stx18 silencing in Mtb-infected NHBE cells resulted in diminished MR1-dependent recognition of infection with Mtb." (PMID 27031111, 2016). "The tight regulation of CD1 and MR1 expression at steady state and during infection may represent an important mechanism to limit autoreactivity, while promoting T cell responses to foreign antigens." (PMID 26284072, 2015). "Together, these data suggest that the increase in MAIT cell frequencies in response to pulmonary LVS infections and early control of the bacteria within the lungs is MR1-dependent, but that IL-12 plays a direct role in the containment of intracellular infection." (PMID 26217338, 2015). "We next investigated whether there is a relationship between MR1 up-regulation and infection levels." (PMID 24432025, 2014). "Additionally, we demonstrate that infection with Mtb induces cell surface expression of MR1 on lung epithelium." (PMID 20613858, 2010). "Considering that HSPCscan be directly infected by various microorganisms, it is plausible that infection with certain pathogens could induce the expression of MR1 and/or NKG2D-Ls on the surface ofHSPCs, potentially triggering an autoimmune attack mediated by MAIT cells." (PMID 39337644, 2024). "In addition, it is possible that FTY720, GK1.5, and MR1 could influence immunity against infection and bacterial burdens; if bacterial clearance rates differed among the various treatments that could contribute to the effects observed." (PMID 38715601, 2024). "cDC1 cells from both uninfected wildtype and uninfected Bcl3flx/flxZbtb46 cre mice expressed similar levels of genes related to antigen presentation except those related to MHC class Ib genes (H2-M3, Mr1, Cd1d), which seemed to be affected by Bcl3 deficiency even in the absence of infection." (PMID 36318581, 2022). "Taken together, these observations refuted the hypothesis that lack of MAIT cell activation is caused by an impaired MR1-dependent antigen presentation following STM-D23580 infection." (PMID 32788367, 2020). "In the context of infection, MAIT cells are rapidly activated after their TCRs recognize bacterial metabolites presented by MR1 on the surface of infected cells." (PMID 41179703, 2025). "MAIT cells accumulate in the murine lung after intranasal infection with these bacteria, and optimal MAIT cell activation and expansion is MR1-dependent and supported by cytokines such as IL-12 in the case of Francisella and IL-23 for Legionella." (PMID 39128630, 2024). "MAIT cell-dependent activation by MR1 leads to the production of inflammatory cytokines IFN-γ, TNF-α, and IL-17 to control infection." (PMID 38003807, 2023). "They must be licensed to produce granzyme B in the context of infection, TCR or MR1-independent cytokine stimulation." (PMID 36085311, 2022). "MR1 is unique among MHC Class I and Class I-like molecules in that very little MR1 is expressed on the cell surface prior to infection despite ubiquitous expression at the RNA level." (PMID 33247182, 2020). "Intracellular infection of wild-type THP1 and THP1.MR1+ cell lines induced expression of tumor necrosis factor (TNF) by human MR1-5-OP-RU tetramer+ MAIT cells." (PMID 30135490, 2018).
infection (continued). "Upon infection, MAIT cells can be activated in a MR1-dependent way by a variety of cells, including DC, macrophages, epithelial cells, and fibroblasts." (PMID 26284072, 2015). "infection, DCs can activate MAIT cells after presenting antigens via MR1." (PMID 41179703, 2025). "MR1-KO mice intranasally infected with PR8 show impaired survival in comparison to WT counterparts, while survival improves by adoptive transfer of pulmonary MAIT cells to immunocompetent and immunodeficient mice prior to infection." (PMID 39128630, 2024). "Unlike other antigen-presenting molecules (MHC-I and MHC-II), in the absence of infection, MR1 is hardly detectable on the surface of human cells." (PMID 39192975, 2024). "Mammals possess a non-classical class I molecule, MR1, which serves as a sensor of microbial metabolomes and should be able to detect intracellular infection early on." (PMID 36593453, 2023). "Although that study defined MAIT cells as CD4−CD8− T cells, here we have precisely identified MAIT cells using MR1-5-OP-RU tetramers, allowing us to detect MAIT cell accumulation as early as 3 dpi, with the peak of MAIT cell numbers observed at day 6 post infection in most organs." (PMID 34272362, 2021). "MR1 preparations from either infection contained ions with an ionization pattern not consistent with ribityllumazine molecules." (PMID 32983150, 2020). "It is thus probable that MR1-antigen production, and the resultant MAIT cell activation, may be enhanced under different conditions that may be encountered during the course of infection." (PMID 32973800, 2020). "An intranasal infection of Francisella tularensis live-vaccine strain (LVS) in wild-type and MR1 KO mice, has also established that CD161++TCRvα7.2+ T cells have a direct early antibacterial effect in the lung and a sustained impact on development of effective adaptive mucosal immune response." (PMID 31497028, 2019). "In addition, we identified and cloned an MR1-restricted, TRAV12–2+ T cell that, although able to bind the MR1/5-OP-RU tetramer, can recognize infection with S. pyogenes, a pathogen that cannot synthesize riboflavin." (PMID 30006464, 2018). "Using tetramers for MR1 or to immunodominant epitopes from the nucleoprotein or polymerase acidic protein of influenza virus, we tracked MAIT cells and conventional antigen-specific αβ T cell accumulation during PR8 infection." (PMID 30413689, 2018). "MR1 transcripts are detected in multiple tissues, but MR1 expression at the cell surface is very low in the absence of infection." (PMID 29326714, 2017). "Mtb-infection of A549 cells resulted in robust IFN-γ production by NC-restricted HLA-E and MR1-restricted T cells, in a manner that was dependent on the HLA-Ib molecules HLA-E and MR1, respectively." (PMID 20613858, 2010). "Using LDA, we find that MR1-specific Mtb-reactive clones predominate in individuals without infection with Mtb." (PMID 20613858, 2010). "Owing to their dual activation mode—antigen recognition mediated by MR1 and nonspecific activation driven by cytokines—along with characteristics such as rapid response and wide distribution, MAIT cells can combat infections caused by various pathogens such as bacteria, viruses, and fungi." (PMID 41179703, 2025). "To assess whether pre-infection with Salmonella Typhimurium BRD509 is necessary for the protective effects of MAIT cells, we evaluated weight loss in WT and Mr1−/− mice, without prior Salmonella Typhimurium BRD509 infection." (PMID 39918959, 2025). "IFNγ production was therefore not completely eliminated by MR1 blockade, but instead it was slowed down, which may be of paramount importance in an acute infection context such as S. aureus bacteraemia." (PMID 35056597, 2022). "Furthermore even by day 3 post infection we observed reduced pulmonary production of IFN-γ and key innate inflammatory cytokines monocyte chemoattractant protein-1 (MCP-1), IL-6 and C-C motif chemokine ligand 5 (CCL5, RANTES) in MR1-/- mice." (PMID 35381137, 2021).
infection (continued). "Interestingly, based on extensive mutagenesis, the 6C2 hybridoma used overlapping but distinct TCR residues for the recognition of MR1 on E. coli infected cells vs. MR1 overexpressing cells in the absence of infection." (PMID 33013835, 2020). "A TRAV1-2− T cell clone (D462-E4, TRAV12-2) reacted to MR1-5-OP-RU tetramer and responded to RL-6-Me-7-OH but not RL-6,7-diMe and in addition to infection with Streptococcus pyogenes which lacks the riboflavin biosynthetic pathway, suggestive of an undefined riboflavin-independent MR1 antigen." (PMID 33013835, 2020). "By sequencing RNA from sorted MR1-5-OP-RU tetramer+ cells derived from either human blood or murine lungs, we define the basic transcriptome of an activated MAIT cell in both species and demonstrate how this profile changes during the resolution of infection and during reinfection." (PMID 31533045, 2019). "These MR1+ β-2M+ EC have a similar phenotype to the Mtb compartment in AEC and may represent a pre-synthesized pool of MR1 that could be loaded in the context of intracellular infection." (PMID 27031111, 2016). "Here we show that the E. coli-derived antigen(s) is resistant to proteinase K digestion and lipid extraction and provide evidence that the MAIT TCR uses overlapping but distinct residues for the recognition of MR1 on infected cells and MR1 overexpressing cells in the absence of infection." (PMID 23342002, 2013). "However, during an infection setting, an intact riboflavin synthesising pathogen would also trigger several toll-like receptors (TLRs) within the antigen presenting cell (APC), resulting in a concomitant delivery of MR1 antigen presentation and innate signals to MAIT cells." (PMID 39110717, 2024). "In addition, while overnight pretreatment of BEAS-2B with 6-FP resulted in the enhanced MR1 presentation of exogenous ligands, this effect was not seen with Mtb infection, supporting the notion of different pathways for an intracellular infection." (PMID 36430890, 2022). "In another model, the absence of MR1 and therefore MAIT cell accumulation in the lungs led to fatal infection." (PMID 34718585, 2022). "In vivo, the absence of MR1 (and therefore MAIT cells) results in failure to control infection as mice lacking MR1 have been shown to have higher bacterial burden in their spleen and lungs compared to wild-type mice." (PMID 33828558, 2021). "Despite the low frequency of MAIT cells in common laboratory strains of mice, they showed that in the absence of MR1, and, therefore, MAIT cells, mice succumbed to disseminated infection, while wild-type mice cleared the infection within 2 days." (PMID 25339949, 2014). "Ex vivo analyses of circulating, MR1-restricted, Mtb-reactive MAIT cells demonstrate that subjects with active TB have substantially lower frequencies than those without evidence of infection with Mtb." (PMID 20613858, 2010). "Protection is dependent on MR1, IFN-γ and GM-CSF, but not IL-17A, TNF or perforin, and enhanced protection is detected earlier after infection of mice antigen-primed to boost MAIT cell numbers before infection." (PMID 30135490, 2018). "However, at day 30 post-infection, the bacterial burden of MR1+/+ and MR1−/− mice were not significantly different." (PMID 26217338, 2015). "HLA-E, CD1, and MR1 present non-self-lipids, peptides, and metabolites separately that could be recognized by TCR, indicating that T cells have additional roles in immune responses to tissue homeostasis, inflammation, infection, and cancer." (PMID 33185693, 2020).
tumor (69 papers, 2011 to 2026). "The function of MR1-restricted mucosal-associated invariant T (MAIT) cells in tumor immunity is unclear." (PMID 34362900, 2021). "MR1 mutations have been found to reduce surface antigen presentation and anti-tumor response in MAIT cells, and amongst GTEx tissues, MR1 mRNA is most highly expressed in the urinary bladder." (PMID 33919687, 2021). "Therefore, according to these experiments, expression of MR1 with the tumor antigen can cause cancer destruction by T-cells." (PMID 40362653, 2025). "This knowledge could also help explain MAIT cell cytotoxic effects in vitro, or, considering the increased tumor growth observed in MR1-deficient mice, which tumor antigen might activate MAIT cells in a pro-inflammatory or tumor-promoting state." (PMID 33805904, 2021). "However, there are example cases of TCRs targeting common HLA alleles such NY-ESO-1 mutated antigens on HLA-A0201, or TCR targeting ubiquitous molecules such as tumour-associated MR1." (PMID 32630096, 2020). "As the unknown metabolite antigen or antigens presented by MR1 are specific to or associated with cancer, they may represent a novel class of neoantigens, beyond the neo-peptides arising from altered tumor proteins and presented by classical MHC-I or MHC-II." (PMID 32756356, 2020). "MR-1 may promote cancer cell proliferation by binding to specific proteins, such as eukaryon initiation factor 3, which is highly associated with the regulation of tumor cell growth and invasion." (PMID 21702971, 2011). "The cognate interaction between TCR and MR1 was confirmed with soluble TCR and tumor-cell-derived soluble MR1 molecules." (PMID 40040716, 2025). "This specific recognition mechanism enables MAIT cells to launch immune attacks against tumor‐specific antigens presented by MR1, thereby inhibiting tumor growth and spread." (PMID 41179703, 2025). "Recent findings reveal that nucleoside and nucleobase analogs, as self-metabolites to activate MR1-restricted T cells, are regulated in the tumor microenvironment." (PMID 40746558, 2025). "Early preclinical studies report efficient in vitro tumor cell killing, and MR1-restriction plus MHC-independence should favor off-the-shelf allogeneic use with reduced GvHD risk." (PMID 41194129, 2025). "Tobacco components (such as benzaldehyde derivatives) bind to MR1 protein and block the activation of MAIT cells by bacterial metabolites, further exacerbating the susceptibility to pulmonary infections and tumor progression." (PMID 41179703, 2025). "In the tumor microenvironment (TME), MAIT cells can bind to the antigen‐presenting molecule MR1 on tumor cells, thereby exerting antitumor effects." (PMID 41179703, 2025). "Of note, most of these DM/DE genes were hypomethylated and overexpressed in the MR1/Myf5 compared to the MR2/Pax7 tumours." (PMID 39812007, 2025). "Overall, MR1-restricted T cells display functional plasticity with tumor-suppressive or tumor-promoting responses across various malignancies, reflecting the dynamic influence of the tumor microenvironment." (PMID 40746558, 2025). "MR1-restricted TCRs specific to tumor cells have been described, raising interest in their potential therapeutic application for cancer treatment." (PMID 39445059, 2024). "When expressed in Jurkat cells, the A4 and C1 TCRs responded to MR1*01-expressing tumor cell lines, as shown by upregulation of CD69." (PMID 39445059, 2024). "The results indicated that MR‐1 was highly expressed in tumor tissues compared with adjacent non‐tumor lung tissues." (PMID 38342606, 2024). "It has been suggested that regulatory T cells MAIT cells can promote immune escape through the action of the MR1 molecule on the surface of tumor cells." (PMID 39039547, 2024). "We also detected the expression of Epithelial‐mesenchymal transition (EMT) related proteins in the tumor by Western Blotting, and found that MR‐1 can promote EMT." (PMID 38342606, 2024).
tumor (continued). "Due to the plasticity of the antigen-binding cleft, non-riboflavin antigens such as microbial molecules and tumor cell-derived molecules can bind to MR1, adding to the diversity of MR1 ligands." (PMID 38550591, 2024). "The interaction with MR-1 expressed on tumor cells and TIME MAIT cells activate them to release IL-17A, suppressing cytotoxic T and NK cells." (PMID 37508372, 2023). "Non‐MAIT, MR1‐restricted T cells were recently shown to recognise tumor cells in an MR1‐dependent manner, suggesting the existence of tumor‐derived antigens presented by MR1." (PMID 35028137, 2022). "An important and additional indication that the MR1 antigen-binding capacity is broader than currently appreciated comes from the identification of MR1T cells that recognize tumour cells." (PMID 34718585, 2022). "For example, MAIT cells were found to exert tumor‐promoting functions, with improved outcomes in MAIT cell‐deficient MR1−/− mice." (PMID 35028137, 2022). "In this regard, it is worth noting that B16F10 is one of the tumor cell lines which strongly upregulate MR1 upon 5-OP-RU exposure, thus facilitating early activation of MAIT cells." (PMID 36551916, 2022). "MR1-expressing tumor cells activate MAIT cells to reduce NK-cell effector function, partly in a manner depending on the production of IL-17A." (PMID 36032082, 2022). "The microbial compounds identified so far and the indirect evidence obtained with MR1T recognition of tumour cells suggests that MR1 exerts the role of a promiscuous metabolic sensor capable of alerting the immune response." (PMID 34718585, 2022). "The fact that MR1 is oligomorphic and that many tumours stimulate these cells implies that it is possible to exploit MR1T TCRs as off-the-shelf TCRs, ready for immediate use in cell therapy." (PMID 34718585, 2022). "MR1T cell clones have been identified by their ability to react to self-antigens presented by tumour cells and other healthy cells in an MR1-restricted manner." (PMID 34718585, 2022). "Whereas the tumor-MR1-dependent suppression of NK cell functions, such as repression of IFN-γ, is attributed to MAIT cells, MAIT-cell-dependent activation of NK cells in the presence and/or absence of 5-OP-RU has been reported." (PMID 36551916, 2022). "Expression of the NK cell receptors DNAM-1, CD96 and NKG2D, the degranulation marker CD107a, and the cytokines IFN-γ and TNF, were similar in NK cells derived from tumor bearing B6-MAITcast MR1 WT and B6-MAITcast MR1−/− mice." (PMID 34362900, 2021). "Local activation of MAIT cells within tumours was suggested to be possible due to the co-expression of MR1 with the invariant MAIT TCR in 10 out of 11 kidney tumours." (PMID 33808058, 2021). "To confirm this, we evaluated the effect of 5-OP-RU pulsing on the metastasis of B16F10 tumor cells following CRISPR/Cas9-mediated deletion of MR1." (PMID 34362900, 2021). "Of note, tumor cell-derived MR1-restricted Ags have been recently identified but were shown to activate non-MAIT MR1-restricted T cells." (PMID 34298791, 2021). "Non-MAIT, MR1-restricted T cells were recently shown to recognize and kill several varieties of tumor cells in an MR1-dependent manner." (PMID 33805904, 2021). "The authors elegantly demonstrated that MAIT cells suppress NK cell anti-tumour effector functions in a MR1 and IL-17 dependent manner, providing mechanistic evidence for a pathogenic role for MAIT cells." (PMID 33808058, 2021). "These pathways were also enriched in NK cells isolated from tumor bearing B6-MAITcast MR1 WT mice pre-treated with 5-OP-RU, highlighting that activation of these pathways is potentially associated with reduced metastatic burden." (PMID 34362900, 2021). "This suggests that endogenous MR1 expression on B16F10 tumor cells is sufficient for the anti-tumor response observed following pulsing with MAIT cell antigens." (PMID 34362900, 2021).